IRS1 (insulin receptor substrate 1)
Diseases named in the same sentence as IRS1 in open-access papers (continued):
Sharing a sentence is not in itself a finding about the gene and the disease.
nonalcoholic fatty liver disease (8 papers, 2012 to 2025). "This study was designed to investigate the possible effect of the insulin receptor substrate 1 (IRS1) gene rs1801276 polymorphism on the risk of nonalcoholic fatty liver disease (NAFLD)." (PMID 39420901, 2024). "Vitexin, on the other hand, is shown to improve insulin signalling in non-alcoholic fatty liver disease (NAFLD) mice through upregulation of insulin receptor substrate-1 (IRS-1) and also its downstream target AKT." (PMID 35458200, 2022). "Consistent with this notion, Irs1 expression was maintained or rather increased, and Irs2 expression was reduced in the liver biopsy specimens obtained from patients with nonalcoholic fatty liver disease (NAFLD)." (PMID 27708333, 2016). "Hepatitis C can induce a chronic inflammatory state, and inflammatory cytokines are related to decreased expression of IRS1 in nonalcoholic fatty liver disease." (PMID 22830036, 2012). "Also, it attenuated the expression of p‐JNK1/2/3, phospho‐NF‐κB p65, phospho‐insulin receptor substrate 1 (IRS1), phospho‐IKK α/β, and elevated the level of x‐box‐binding protein 1 (XBP1), GSH, vitamin C, Nrf2, SOD, CAT, and GPx in nonalcoholic fatty liver disease in fructose‐fed mice." (PMID 37457142, 2023).
bladder cancer (7 papers, 2013 to 2023). "They found that overexpression of miR-145 led to inhibition of IGF-1-induced cell proliferation and miR-145 was shown to directly bind to 3′UTR of IGF-1R and IRS-1 in the bladder cancer cells." (PMID 25628647, 2014). "In endometrial carcinoma, the effect on cell cycle has been confirmed and its impairment of apoptosis has been described and miR-96 controls invasion and differentiation in bladder cancer cell lines via regulation of IRS1 and MAP4K1." (PMID 24260486, 2013). "Interestingly, study demonstrated that cells of human bladder cancer transfected with hsa-miR-96 inhibitor significantly reduced the growth of bladder cancer cells through reduction of mRNA and protein levels of IRS1." (PMID 28373897, 2017). "In addition, in bladder cancer cell J82 with down-regulated expression of CHAF1A, some down-regulated expression of several genes related to cell growth and proliferation were found, including STAT2, STAT6, AKT2, IRS1 and SOX4." (PMID 37575547, 2023).
depression (7 papers, 2020 to 2025). "Recent years, some findings suggested that aberrant hippocampal IR/IRS-1 signaling was associated with depressive disorders." (PMID 34149862, 2021). "Preclinical models demonstrate that chronic stress and hypercortisolism in depression impair insulin signaling through glucocorticoid receptor-mediated suppression of IRS-1 phosphorylation." (PMID 40904459, 2025). "For example, ISR-1 in neuron-derived EVs was related to the feeling of guilt, suicidality and anhedonia, while a higher level of pSer-IRS-1 was correlated to an aggravated severity of depression in females." (PMID 36923936, 2023). "Consequently, our findings suggest that both neuronal and astrocytic IR/IRS-1 signaling pathways make important contribution to the treatment of ZJJ on diabetes-related depression." (PMID 34149862, 2021). "In fact, the regulation on the neurobehavioral by IR/IRS-1 signaling could partly attribute to its regulation on brain glucose utilization, which plays an important role in the major depressive disorder." (PMID 34149862, 2021). "This study aims to investigate whether the brain IR/IRS-1 signaling pathway is involved in the therapeutic effect of ZJJ on depression-like behavior in diabetic rats." (PMID 34149862, 2021). "Compared to healthy controls, the number of L1CAM rich exosomes was increased in patients with major depressive disorder (MDD), and these patients had increased concentrations of insulin receptor substrate −1 (IRS-1) in L1CAM+ exosomes, which is associated with suicidality and anhedonia." (PMID 34588957, 2021). "Therefore, we hope to reflect energy metabolism in the brain by detecting energy metabolism indicators such as mitochondrial-related proteins and IRS-1 in plasma brain-derived EVs, which provides a new idea for us to explore the energy metabolism mechanism of depression." (PMID 36970289, 2023). "Therefore, ZJJ regulates energy metabolism in the hippocampus of diabetic rats with depression, which may be related to its regulation on neuronal IR/IRS-1 signaling." (PMID 34149862, 2021).
endometrial cancer (7 papers, 2007 to 2024). Primary or metastatic malignant neoplasm involving the endometrium (mucous membrane that lines the endometrial cavity). "The invasion behavior of endometrial cancer is associated with the activation of the insulin receptor IRS1." (PMID 39205919, 2024). "Activation ofinsulin receptor (INSR), insulin receptor substrates -1(IRS-1) and AKT has also been linked to the invasivenature of endometrial cancer, and insulin has mitogenic and anti-apoptotic properties forthese cells." (PMID 36273315, 2022). "Adiponectin can not only inhibit the proliferation and migration of endometrial cancer cells through the AMPK/mTOR/S6K1 signaling pathway but can also enhance the sensitivity of endometrial cancer cells to insulin through the AMPK/S6K1/IRS1 signaling pathway." (PMID 31440472, 2019). "We first examined the expressions of P-LAP/IRAP, GLUT4, IR, and IRS-1 in human endometrial carcinoma tissues by immuohistochemistry." (PMID 17233921, 2007).
medulloblastoma (7 papers, 2009 to 2023). A malignant, invasive embryonal neoplasm arising from the cerebellum. "IRS-1 has been implicated in the development of medulloblastomas through an interaction with the T-antigen of human polyomavirus JC (JCV T-antigen)." (PMID 19534786, 2009). "However, in medulloblastoma, an enhanced ERβ activity has been associated with nuclear translocation of insulin receptor substrate 1 (IRS-1), which interacts with RAD51 at the sites of damaged DNA and reduces the HR function." (PMID 29498642, 2018). "In medulloblastomas, IRS-1 translocates to the nucleus with ERβ or the JCV T-antigen, where it interacts with Rad51 and prevents HRR, rendering these tumors more sensitive to genotoxic agents such as cisplatin." (PMID 19534786, 2009). "In other cancers, including breast, ovarian and medulloblastoma, only IRS-1 expression has been evaluated and a similar trend toward increased expression in primary tumors has been reported." (PMID 19534786, 2009). "Furthermore, IRS1 regulates the nuclear localization of YAP1, which causes the proliferation of cerebellar neural precursors in hedgehog-associated medulloblastomas." (PMID 36768755, 2023). "We have previously reported that ERβ, which is highly expressed in medulloblastomas, translocates insulin receptor substrate 1 (IRS-1) to the nucleus, and that nuclear IRS-1 binds to Rad51 and attenuates homologous recombination directed DNA repair (HRR)." (PMID 22439007, 2012). "We also examined by immunohistochemistry the expression of IRS1, Akt/Pkb and Erk1/2 kinases, downstream mediators of the IGF-I signaling pathway, in medulloblastoma samples from Ptc1+/- and Ptc1+/-/IGF-I Tg mice (n = 3)." (PMID 20214787, 2010). "Medulloblastomas from Ptc1+/- and Ptc1+/-/IGF-I Tg mice also express IRS1, and show Akt and Erk 1/2 activation, demonstrating a functional role for the IGF-I signaling system in medulloblastoma formation." (PMID 20214787, 2010). "Disruption of the interaction between IRS-1 and the JCV T-antigen using a dominant negative mutant of IRS-1 inhibits the anchorage-independent growth and survival of JCV T-antigen transformed medulloblastoma cells." (PMID 19534786, 2009). "Medulloblastoma cell lines and biopsies express high levels of the IGF-1R and IRS-1, the latter of which co-localizes with the JCV T-antigen in the nucleus." (PMID 19534786, 2009).
non-small cell lung carcinoma (7 papers, 2009 to 2023). A group of at least three distinct histological types of lung cancer, including non-small cell squamous cell carcinoma, adenocarcinoma, and large cell carcinoma. "Decreased IRS-1 expression is also observed in some non-small cell lung cancers (NSCLC), and this lower expression occurs more frequently in squamous cell carcinomas." (PMID 19534786, 2009). "There is a relationship between IRS-1 and 2 and various types of cancer, such as breast, lung, prostate, hepatocarcinoma, neuroblastoma, head and neck, colorectal, esophageal squamous cell carcinoma, non-small cell lung cancer, and glioblastoma multiforme." (PMID 36975518, 2023). "miR-7-5p is more of a tumor suppressor that represses oncogenic proteins such as EGFR, IGF1R, IRS-1, IRS-2, RAF1, PIK3CD, mTOR, and PI3K, in various cancers including PDAC, liver, breast, non-small cell lung carcinoma (NSCLC), colorectal (CRC) and ovarian." (PMID 31510100, 2019). "IRS-1 and IRS-2 expression in normal lung and non-small cell lung cancer were evaluated by immunohistochemistry (IHC)." (PMID 31393907, 2019).
osteoporosis (7 papers, 2018 to 2025). A condition of reduced bone mass, with decreased cortical thickness and a decrease in the number and size of the trabeculae of cancellous bone (but normal chemical composition), resulting in increased fracture incidence. "Our findings demonstrated that E2 and vitamin D exhibited synergistic efficacy in preventing osteoporosis by modulating the miR-351-5p/IRS1 axis and inhibiting the mTOR/NFκB signaling pathway." (PMID 40436926, 2025). "In conclusion, E2 and vitamin D exhibited a synergistic effect in preventing osteoporosis through the miR-351-5p/IRS1 axis and mTOR/NFκB signaling pathway." (PMID 40436926, 2025). "This study confirms that E2 and vitamin D synergistically ameliorate osteoporosis by inhibiting the miR-351-5p/IRS1 axis and the mTOR/NFκB pathway." (PMID 40436926, 2025). "In BMSCs, IRS-1 could significantly promote osteogenic differentiation by increasing TAZ expression, which makes IRS-1 a potential therapeutic target for mitigating osteoporosis by stem cell therapy in the near future." (PMID 30530508, 2018). "In summary, our data demonstrates a close interaction between IRS-1 and TAZ during bone formation, indicating that IRS-1 may be a promising target for the development of new therapeutic treatments for osteoporosis." (PMID 30530508, 2018). "Thus, we speculate that the E2 and vitamin D combination treatment may exert preventive effects on osteoporosis by modulating the miR-351-5p/IRS1 axis." (PMID 40436926, 2025). "Differential expression analysis in osteoporosis and sarcopenia datasets revealed that seven biomarkers—BCL6, DDIT4, FOXO1, IRS1, NFKBIA, PGK1, and STAT3—were differentially expressed in the independent osteoporosis dataset GSE84500." (PMID 41282482, 2025). "Next, we will further explore the direct target of miR-690 regulating IRS-1/TAZ in primary cells, and verify the positive role of M2D-exos in osteoporosis animal models." (PMID 34295306, 2021).
ovarian carcinoma (7 papers, 2013 to 2025). A malignant neoplasm originating from the surface ovarian epithelium. "Analysis of data sets from GDC TCGA Ovarian Cancer confirmed the amplification of both IRS1 and IRS2 genes, associated with decreased overall survival rates in ovarian cancer patients." (PMID 38272982, 2024). "Studies have shown that malignant behaviors, including migration and invasion, of ovarian cancers depend on both IRS1 and IRS2 through the activation of the PI3K/AKT pathway." (PMID 38272982, 2024). "Of special attention is the description of the expression levels of genes such as POSTN, CHI3L1, CAV-1, IRS1, DCN, which according to literature data are associated with diseases such as POI, PCOS, and ovarian cancer." (PMID 34827207, 2021). "RSV effectively reversed the BG-1 ovarian carcinoma cell proliferation induced by E2, down-regulating the expression of ER, cyclin D1, IGF-1R and activation of Insulin Receptor Substrate 1 (IRS-1) and AKT." (PMID 30832393, 2019). "We measured these signaling proteins phosphorylation by western blot and observed variable inhibition of phosphorylated IRS-1, AKT, and MAP kinase expression in epithelial ovarian cancer cells by AS." (PMID 24103397, 2013). "Other signaling pathways such as IRS1/2, PI3 K and AKT were not involved in IL-13 signaling in ovarian cancer cell lines." (PMID 30572904, 2018).
Stroke (7 papers, 2012 to 2023). Sudden impairment of blood flow to a part of the brain due to occlusion or rupture of an artery to the brain. "IHC study of human AD/stroke patients revealed co-localization of mCRP with Aβ plaques, tau-like fibrils and IRS-1/P-Tau positive neurons and high mCRP-levels spreading from infarcted core regions matched reduced expression of Aβ/Tau." (PMID 26335098, 2015). "The integral role of IRS-1 in facilitating skeletal muscle growth and regeneration is well established; therefore, loss of IRS-1 via Cblb may contribute to stroke-induced skeletal muscle atrophy." (PMID 32629989, 2020). "Indeed, the impairment of the IRS1/2/PI3K/Akt pathway (triggering insulin signaling) leads to the loss of pro-angiogenic, anti-oxidative and anti-inflammatory actions in genetically obese Zucker rats and studies as such should also be performed in the brain after stroke." (PMID 36835405, 2023). "In human AD/stroke patients, a co-localization of monomeric CRP (mCRP) with Aβ plaques, tau-like fibrils and insulin receptor substrate 1 (IRS-1)/Phospho-Tau positive neurons was reported, and the authors suggested mCRP may be responsible for promoting dementia after ischemia." (PMID 33671099, 2021).
type 1 diabetes (7 papers, 2010 to 2025). "While prior studies have partially elucidated the role of insulin signaling in corneal nerve repair in type 1 diabetes, our preliminary data show that p-insulin receptor substrate 1 (p-IRS1) expression in diabetic corneal epithelia correlates with p-AKT levels; ADPN treatment upregulated both." (PMID 41146365, 2025).
cardiac hypertrophy (6 papers, 2016 to 2025). "Consistently, a cardiac-specific knockout of insulin receptor substrate 1 (IRS1) has prevented cardiac hypertrophy and fibrosis." (PMID 36979641, 2023). "Further, there are high resistin levels in cardiomyocytes derived from type 2 diabetic hearts, with resistin overexpression altering cardiac contractility and promoting cardiac hypertrophy potentially through the IRS1/MAPK pathway." (PMID 35069436, 2021). "Studies of mice with cardiomyocyte-specific deletion of either insulin receptor substrate 1 (IRS1) (CIRS1KO mice) or IRS2 (CIRS2KO mice) reported that at baseline, adult CIRS1KO hearts were reduced in size, whereas CIRS2KO hearts exhibited cardiac hypertrophy." (PMID 27148064, 2016).
cardiomyopathy (6 papers, 2013 to 2024). A disease of the heart muscle or myocardium proper. "Incomplete or disrupted insulin signaling contributes to cardiomyopathy via two key pathways: insulin receptor substrate-1 (IRS-1) and mitogen-activated protein kinase (MAPK)." (PMID 32842567, 2020).
cervical cancer (6 papers, 2017 to 2026). A primary or metastatic malignant neoplasm involving the cervix. "The objective of this study was to investigate which isoform of the insulin receptor is expressed in the HeLa cervical cancer cell line and to analyze the role of IRS-1 and IRS-2 in the signaling pathway of the insulin receptor and in regulating the proliferation and migration of HeLa cells (HPV+)." (PMID 36975518, 2023). "Our findings highlight IRS1 and the PI3K pathway as a potential therapeutic target for cervical cancer in women living with HIV-1." (PMID 42305618, 2026). "The relationship between the expression levels of IRS-1 and IRS-2 and the activation of insulin signaling pathways has been poorly studied in cervical cancer cells." (PMID 36975518, 2023). "We study the participation of the insulin substrates IRS-1 and IRS-2 in the insulin signaling pathway in response to insulin and their involvement in the proliferation and migration of the cervical cancer cell line." (PMID 36975518, 2023). "A PPIN of 90 genes identified FLT1, IGF2, IRS1, JUN, KDR, ZEB1, TIMP2 (downregulated), and EZH2, SOX2, and MYB (upregulated) in cervical cancer samples when compared with normal samples." (PMID 36879084, 2023). "It has been reported that progesterone upregulates IRS-2 expression, altering the levels of IRS-1 and IRS-2 in HeLa cells expressing progesterone receptors; however, very little is known about the role of the insulin signaling pathway in cell proliferation and migration in cervical cancer." (PMID 36975518, 2023).
diabetic nephropathy (6 papers, 2016 to 2025). "In the glomerulus, deficiency of IRS1-mediated pathway causes glomerular dysfunction and possibly contributes to diabetic nephropathy." (PMID 27247938, 2016). "In the glomerulus, the impairment of IRS1 signaling deteriorates the structure and function of podocyte and endothelial cells, possibly causing diabetic nephropathy." (PMID 27247938, 2016). "Of note, GWAS has some limitations, as: a) miRNAs are rarely prioritized in GWAS due to their regulatory roles, but transcriptomic studies link miR-342-5p to insulin signaling (e.g., suppression of IRS1 in adipose tissue) and miR-636 to autophagy in diabetic nephropathy." (PMID 40533788, 2025).
glucose metabolism disorder (6 papers, 2016 to 2025). "ameliorates insulin sensitivity and glucose metabolism disorders by regulating the IRS1/PI3K/AKT signaling pathway and the expressions of its downstream targets GLUT4, FOXO1, and GSK3β." (PMID 40351361, 2025). "As a result, the deactivation/dephosphorylation of IRS1 would lead to the impairment of insulin effect, such as the glucose metabolism disorder and lipid metabolism disorder." (PMID 27054886, 2016). "In conclusion, hepatic IRS1 expression was inversely correlated with NAFLD histologic changes and could be a cause of glucose metabolic disorders, which are typically observed with NAFLD." (PMID 29749571, 2018). "By stimulating the IRS-1/PI3K/AKT signaling system, SE-PP controlled glucose metabolism disorder in adipose tissue, while also inhibiting the TLR4/MYD88/NF-κB pathway to reduce inflammation." (PMID 40941124, 2025).
Hypoglycemia (6 papers, 2019 to 2024). A decreased concentration of glucose in the blood. "Our findings suggest that DSS potentially confers cognitive protection by alleviating central hypoglycemia through the IRS1/GSK3β/Wnt3a‐β‐catenin pathway." (PMID 39344343, 2024). "Numerous investigations have demonstrated that puerarin can cause hypoglycemia via increasing the expression of PPARα, insulin-like growth factor-1 (IGF-1), and insulin receptor substrate-1 (IRS-1)." (PMID 38666911, 2024). "Interestingly, inhibitory serine residues of IRS1 can also be O-GlcNAcylated leading to the possibility of hypoglycemia mediated reduced O-GlcNAcylation on inhibitory serine residues of IRS1 that may result in its increased phosphorylation and development of impaired insulin signaling in AD brain." (PMID 31143098, 2019). "Phip encodes for a protein that binds to the insulin receptor substrate 1 (Irs1) and is hypothesized to act as a link between Irs1 and the insulin receptor, thus modulating the insulin pathway; mice lacking Phip1, the main isoform of Phip, develop hypoglycemia and have a short lifespan." (PMID 37891482, 2023).
intrauterine growth restriction (6 papers, 2014 to 2026). "The higher protein content and response to IGF-I of IGF-IR, IRS-1, and AKT observed in SGA placentas may represent a compensatory mechanism in response to fetal growth restriction." (PMID 25050889, 2014).